EGFR (epidermal growth factor receptor)
Diseases named in the same sentence as EGFR in open-access papers (continued):
Sharing a sentence is not in itself a finding about the gene and the disease.
tumor (continued). "However, the highest significant correlation was observed between EGFR mutation and the occurrence of seizures as the clinical onset of the neoplasm (p = 0.004)." (PMID 37240478, 2023). "However, TCBs commonly cause off-tumor tissue toxicity due to low levels of tumor antigens in healthy tissues (e.g., EGFR)." (PMID 38106674, 2023). "Moreover, tumor biopsies during the study revealed that clinical response to therapy was associated with the suppression of EGFR and HH genes." (PMID 37626893, 2023). "Furthermore, the H3-WT tumours with ACVR1 mutations had higher expression levels of EZHIP than H3-WT tumours with EGFR mutations." (PMID 36882456, 2023). "utilized patient-derived non-small cell LCOs to explore drug resistance and found that elevated expression of tumor CD73 in patients with EGFR mutation contributes to the immunologically quiescent microenvironment of EGFR-mutant NSCLC, leading to immune checkpoint therapy resistance." (PMID 37941550, 2023). "However, patients eventually develop TKI resistance and tumor relapses due to the occurrence of secondary EGFR mutation, T790M." (PMID 37495186, 2023). "Patients with tumor mutations in the erythroblastic leukemia viral oncogene homolog (ErbB) family, including EGFR and ErbB2, had a significantly shorter disease-free survival than those with wild-type EGFR or ErbB2." (PMID 36149029, 2023). "The commonly used pathology technique to assess EGFR mutation status is the biopsy, which is time-consuming and expensive, and its accuracy is affected by tumor heterogeneity; moreover, many patients cannot be tested through biopsy due to health conditions and other reasons." (PMID 36983578, 2023). "Liquid biopsy of circulating tumour DNA (ctDNA) is increasingly used to detect EGFR mutations, including main activating alterations (exon 19 deletions and exon 21 L858R mutation) and T790M mutation, which is the most common mechanism of acquired resistance to first- and second-generation TKIs." (PMID 37047382, 2023). "It appears that the AT1R pathway seems to be the basic RAAS pathway that is implicated in tumor development, tumor proliferation, and angiogenesis by increasing the expression of epidermal growth factor receptor (EGFR) or vascular endothelial growth factor (VEGF)." (PMID 37891636, 2023). "In CCA, EGFR was associated with large tumour size which could be explained by the role of EGFR in induction of the proliferative activity and tumour growth." (PMID 38414954, 2023). "Therefore, while the Thr790Met mutation itself is not directly oncogenic, it is considered pathogenic because it allows tumor cells to continue growing and spreading even in the presence of TKIs, which are the standard of care for EGFR-mutant NSCLC." (PMID 37508780, 2023). "This is probably due to the tumor immune microenvironment of EGFR mutant NSCLC, which is associated with uninflamed characteristics, low PD-L1 (programmed death-ligand-1) expression/CD8+ TILs (Tumor-infiltrating lymphocytes), and a low tumor mutational burden (TMB)." (PMID 37240224, 2023). "We found that EGFR mutations or TERT mutations might have prognostic value for the tumour recurrence of NMIBC." (PMID 37892022, 2023). "In the analysis of tumor size, we found that the percentage of nodules ≤ 1 cm in the other gene mutation (n = 45, 78.9%) or the wildtype gene group (n = 95, 87.2%) was higher than in the EGFR mutation group (n = 58, 58.6%) (P < 0.001)." (PMID 37124493, 2023). "An activating EGFR-mutation (L858R) had been detected in the tumor specimen." (PMID 39516993, 2023). "In some cases, only a small percentage of tumour cells has the specific EGFR mutation." (PMID 37376053, 2023). "A recent study using single-cell RNA sequencing confirmed the existence of diverse tumor cell subpopulations associated with EGFR TKI-tolerance, including epithelium development, epithelial-to-mesenchymal transition, drug metabolism vesicle mediated transport, and cholesterol homeostasis." (PMID 37920509, 2023).
tumor (continued). "In general, these results suggested fast tumor cell proliferation might associated with poor prognosis of patients with both EGFR mutations and amplifications." (PMID 36720864, 2023). "In summary, the diagnosis is clear: secondary malignant tumors of bone with unknown primary focus stage IV (EGFR19del, EGFR amplification), tumor mutation burden-L." (PMID 36701708, 2023). "In addition, we found that high LUAD-RS was associated with the tumor recurrence of LUAD patients with positive EGFR mutation in the GSE31210 data set." (PMID 36969247, 2023). "An increase in the practice of liquid biopsy testing for EGFR mutation detection both at diagnosis and at tumour progression may be beneficial for improved TATs." (PMID 37713929, 2023). "The retrograde trafficking of EGFR towards the nucleus was a tumor-specific event that could be driven by the association with MUC1 or a loss of polarity, and these data prompted us to evaluate targeting this pathway therapeutically." (PMID 36253541, 2023). "However, no study focusing on the role of immuno checkpoint inhibitor (ICI) based treatments for EGFR mutated NSCLC patients who carried programmed death ligand 1 (PD-L1) tumor proportion score (TPS) greater than 50% progressed after EGFR-TKI therapy." (PMID 37266427, 2023). "In P02 and P43, EGFR TKI was administrated and concurrent‐resistant mutation EGFR T790M was detected with KDD in tumor tissue or plasma after the patients progressed on the treatment, suggesting KDD was unlikely to be the cause of drug resistance in P02 and P43." (PMID 36325957, 2023). "Their findings indicated that tumor volume, texture, and gradient characteristics could predict EGFR mutation status." (PMID 38027000, 2023). "As a consequence, ARF6 was shown to be involved in EGFR-dependent tumours inducing invasion and EMT and linked to prognosis, further suggesting that a deregulation of MV biogenesis may contribute to cancer progression." (PMID 37296932, 2023). "In summary, these variances in CD39 expression may be explained by the genetic background of tumours, suggesting that EGFR mutations integrate immunological, metabolic, and environmental signals to regulate the immune response." (PMID 38087217, 2023). "Thus, our molecular subtype of EGFR mutations revealed that these PDC models can be used to verify the heterogeneous tumor environment affecting drug responses." (PMID 36717865, 2023). "If the discordant results come from the difference in the range of detectable variants of each test the tumors harboring the mutation may be predominant in the whole tumor, therefore good EGFR-TKI efficacy is expected in these cases." (PMID 37612335, 2023). "Thus, the bottleneck for chemotherapy with EGFR inhibitors is the emergence of resistance mutations in the same tumor, which leads to a decrease in the effectiveness of cancer therapy." (PMID 37754201, 2023). "Thus, this study aimed to explore a novel approach based on 18F-fluoro-2-deoxy-2-deoxyglucose (18F-FDG) PET/CT and serum tumor markers (STMs) to determine EGFR mutation status in male patients with non-small-cell lung cancer (NSCLC)." (PMID 37014455, 2023). "Additionally, intra-tumor heterogeneity among the postulated molecular mechanisms have been found to be associated with resistance to EGFR-TKI therapy." (PMID 36670497, 2023). "Differences in the tumor microenvironment may be the reason why patients with different subtypes of EGFR mutations respond disparately to ICIs." (PMID 37723846, 2023). "Notably, cetuximab has therapeutic potential by targeting EGFR that is abundantly expressed in tumor cells to restrict tumor feeding and ultimately cause cell death." (PMID 37933283, 2023). "Genetic mutation EGFR influences tumor immunogenicity by regulating PD-L1 expression and TMB." (PMID 37090727, 2023).
tumor (continued). "Similarly, in a colitis-associated carcinogenesis model, EGFR signaling in macrophages plays a critical role in tumor development by activating macrophages and inducing polarization toward a tumor-promoting M2-like phenotype." (PMID 37601668, 2023). "Indeed, certain somatic tumor mutations such as T790M in EGFR detected in blood have clinical validity for the EGFR tyrosine kinase inhibitor selection in NSCLC." (PMID 37444467, 2023). "Approximately 40% of the patients with tumor EGFR mutations that cannot be detected in ctDNA by qPCR assays at baseline could still benefit from the EGFR-TKI therapy." (PMID 36835972, 2023). "However, anti‐EGFR targeted treatments are ineffective in tumours with activating mutations in KRAS, NRAS and BRAF." (PMID 37604687, 2023). "By using a combination of tissue morphology classification models and expert pathologist review of high-attention patches to assess signal distribution, we found that our model learns to consider both tumor morphology as well as non-tumor morphologies when predicting EGFR mutational status." (PMID 36927889, 2023). "The 1-year tumor control rates were 81.6% (EGFR wild-type group) and 92.8% (EGFR mutation group)." (PMID 36676186, 2023). "Given that common EGFR mutations could efficiently activate EGFR kinase activity and promote tumorigenesis, it is highly unlikely that a single tumor would acquire two EGFR common mutations simultaneously." (PMID 36829178, 2023). "As a result, we suspect that the two different EGFR common mutations might mainly reside in different tumor cells." (PMID 36829178, 2023). "However, EGFR mutations were detected inconsistently, with an overall consistency of 56.3% between the tumor tissue and the corresponding plasma samples in seven patients." (PMID 37372399, 2023). "However, NSCLC patients with EGFR mutations show a poor response to anti-PD-1/PD-L1 treatment, which suggests that EGFR is involved in regulating the tumour microenvironment and inhibiting immunotherapy." (PMID 37064089, 2023). "In the advanced stages of NSCLC, the initial clinical application for liquid biopsy was the detection of sensitizing EGFR mutations, which may be associated with an enhanced tumor response." (PMID 37240238, 2023). "G309A-HER2 mutations increase tumor formation due to excessive formation EGFR/HER2 heterodimers." (PMID 37508387, 2023). "Achieved efficient EGFR gene therapy, caused tumor inhibition." (PMID 36873354, 2023). "Finally, the use of EVs as diagnostic tools and putative biomarkers in EGFR-dependent tumours will be described." (PMID 37296932, 2023). "The study found that mutations were detected in the CSF ctDNA of 20 (95.2%) patients, with a detection rate of epidermal growth factor receptor (EGFR) mutations of 57.1% in CSF ctDNA versus only 23.8% in peripheral blood ctDNA and plasma circulating tumor cells (CTCs)." (PMID 36338734, 2022). "In recent decades, with the rapid development in tumor molecular biology, the mutations of the epidermal growth factor receptor (EGFR) and the abnormal fusion of the anaplastic lymphoma kinase (ALK) have been reported, which have been successfully applied in clinical settings as targeted therapies." (PMID 35734411, 2022). "Up to 60% of GBM tumours have EGFR amplification and/or mutation." (PMID 36497413, 2022).
tumor (continued). "Since a lower EGFR-aVAF indicates that fewer cells harbor this driver mutation, the tumor may be more heterogeneously mixed with other mutations that drive carcinogenesis." (PMID 35053473, 2022). "Additional coexisting mutations and the proportion of EGFR mutations can affect PFS, and immunohistochemical analyses of tumor tissue from NSCLC patients treated with first-line EGFR-TKIs have shown that co-occurring PTEN loss and IGFR overexpression correlated with poorer PFS and OS." (PMID 35978803, 2022). "Additionally, FOXO1, a prominent target of the miR-183/96/182 cluster and associated with pro-apoptotic and tumor suppressive properties is downregulated in EGFR-amplified GBM." (PMID 35486213, 2022). "Our findings presented in this report suggest that overexpression of DARPP-32 isoforms in EGFR-mutated NSCLC promotes EGFR:ERBB3 “bypass signaling” that enables tumor cells to evade EGFR TKI monotherapy-induced apoptosis by potentiating oncogenic AKT and ERK signaling." (PMID 34675407, 2022). "Additionally, the in vivo antitumor activity of BLU-701 (a fourth-generation EGFR-TKI) against the C797S resistance mutation has been demonstrated in a PC9 cell line-derived tumor xenograft model." (PMID 36482474, 2022). "However, the low basal level expression of EGFR in normal tissue cells can cause undesirable on-target/off-tumor toxicity and reduce the therapeutic window of anti-EGFR ITs." (PMID 36555466, 2022). "In patients with activating EGFR mutations, the inhibition of the tyrosine kinase activity of EGFR may provide a significant anti-tumor effect." (PMID 36139444, 2022). "Plasma detection of the original EGFR-sensitizing mutation was more challenging in samples from patients with tumor progression exclusively at the brain level, compared with patients diagnosed as having disease progression in other locations (EGFR detection rate of 61.5% vs. 76.3%, respectively)." (PMID 36139605, 2022). "Literature reported that EGFR mutations were seen in 13.1–33.3% of tumor specimens." (PMID 36233370, 2022). "A basic research study found that the acquisition of T790M was associated with a slowing of tumor growth, which might underlie the good prognosis of EGFR-mutated NSCLC with acquired T790M." (PMID 35840951, 2022). "For EGFR, which is also known as a gene with hot spot mutation in multiple tumor types." (PMID 35297220, 2022). "Our results demonstrate that the progression of tumor heterogeneity via both genetic and non‐genetic mechanisms might affect osimertinib sensitivity in tumors with acquired resistance harboring EGFR‐T790M mutation." (PMID 35029047, 2022). "EGFR mutations lead to the activation of downstream signaling pathways in the absence of ligand stimulation, which enhances metastasis and resistance to apoptosis, thereby promoting tumor development." (PMID 36508072, 2022). "In most cases, the baseline RAS/BRAF mutation was also detected at PD, suggesting that these variants might contribute to tumor progression, but also that additional genomic events are required to drive resistance to both anti-EGFR agents and chemotherapy." (PMID 35205799, 2022). "We demonstrate that glutamine antagonism not only increases anti‐tumor CD8+ T cells infiltration of EGFR‐mutated lung tumors, but JHU083 can also significantly potentiate Th1 cell expansion, activation, and memory formation which have not been shown previously." (PMID 35861366, 2022). "Ten phosphosites of 8 protein kinase candidates were significantly regulated in EGFR-mutated tumor." (PMID 36482371, 2022). "The present study aimed to develop and validate several combined models that incorporate radiomics signatures, clinical, and CT morphological features to predict EGFR-mutation tumor status, focusing on the predominant 19del and L858R subtypes in patients with LADC." (PMID 36059655, 2022).
tumor (continued). "Interestingly, in a previous transgenic mouse model, a combination of afatinib and bevacizumab effectively suppressed tumor bearing EGFR 19 deletion/T790M and L858R/T790M mutations compared to treatment by either drug alone." (PMID 35053480, 2022). "Indeed, ddPCR assay revealed that tumor sample #9-T was EGFR 19del mutation-positive, which is in line with the results of our FACS analysis." (PMID 36376325, 2022). "Next, to further check whether the antitumor effect was associated with its inhibition of EGFR signaling, tumor extracted from each group were prepared and analyzed for the expression levels of Ki-67 and P-ERK (Tyr202/204)." (PMID 36467103, 2022). "Additionally, CD73 expression is increased in the tumor cells of NSCLC individuals with EGFR mutations." (PMID 35479081, 2022). "One frequent mutation is the amplification of the receptor tyrosine kinase EGFR, which occurs in almost 60% of primary GBM and is associated with a worse prognosis Increased EGFR activity leads to enhanced signaling in several tumor associated downstream pathways like RAS or PI3K." (PMID 35486213, 2022). "Meanwhile, Zeng and colleagues found that M2-like tumor-associated macrophages-secreted EGF could facilitate epithelial OC metastasis by activating EGFR-ERK signaling and suppressing lncRNA LIMT expression." (PMID 36276992, 2022). "The EGFR pathway regulates cancer-cell proliferation, apoptosis blocking, invasion, and metastasis, and the mutation or overexpression of EGFR exists in different human cancers, which means EGFR is an ideal target for tumor therapy." (PMID 35758066, 2022). "Our previous study suggested that serum tumor markers (STMs) integrated with other clinical factors could be a valuable noninvasive tool for predicting EGFR mutations and ALK positivity in NSCLC patients." (PMID 35624472, 2022). "Therefore, clinicians should also fully consider the presence of BRAF mutations in the tumor before using anti-EGFR treatment." (PMID 35433839, 2022). "Interestingly, concomitant inhibition of FGFR1 and EGFR showed synergistic action on tumor regression in EGFR-mutated, FGFR1-overexpressing xenograft models." (PMID 36482474, 2022). "Therefore, tumor samples with a low percentage of cancer cells carrying EGFR mutations that are often missed by the DNA-based method, can be detected by HX103-based FACS (e.g., surgical sample #9-T)." (PMID 36376325, 2022). "VEGF receptor 2 (VEGFR2) inhibition was reported to enhance the anti-tumor effects of EGFR-TKI in EGFR-mutated NSCLC models by inhibiting not only tumor angiogenesis but also oncogenic signaling in cancer cells, implying a potent role of VEGFR2 signaling in EGFR-mutated NSCLC cell proliferation." (PMID 35650550, 2022). "A recent study showed secretion of exosomes containing T790M-mutated EGFR by gefitinib-resistant NSCLC tumor cells could horizontally confer gefitinib resistance to sensitive recipient cells." (PMID 36185288, 2022). "In this study, we report that the exon location of the original EGFR-sensitizing mutation could drive resistance mechanisms underlying tumor progression in advanced EGFR-positive NSCLC patients under targeted therapies." (PMID 36139605, 2022). "Intraperitoneal injections of EGFR-targeted sgPLK1-cLNPs caused their selective uptake into disseminated ovarian tumors, enabled up to approximately 80% gene editing in vivo, inhibited tumor growth and increased survival by 80%." (PMID 36139078, 2022). "In tumor cells, epidermal growth factor receptor (EGFR) activity may be dysregulated due to mutations, increased gene copy number or protein overexpression." (PMID 36291859, 2022). "Therefore, for all tissues except for the tumor, mean values for the entire 18F-afatinib cohort (EGFR wild type and EGFR mutated) are given." (PMID 35453931, 2022).